EZH2 (enhancer of zeste 2 polycomb repressive complex 2 subunit)
Diseases named in the same sentence as EZH2 in open-access papers (continued):
Sharing a sentence is not in itself a finding about the gene and the disease.
ovarian carcinoma (continued). "High-risk HCMV strains transformed OECs confirming an HCMV-induced epithelial ovarian cancer model and highlighting EZH2 tumorigenic properties." (PMID 37634008, 2023). "Increased expression of EZH2 has been described in most common gynecologic malignancies such as cervical, endometrial and ovarian cancer." (PMID 38146588, 2023). "In line with the critical role of EZH2 in epithelial ovarian cancer, EZH2 overexpression was detected in CTO-DB and BL compared to uninfected OECs." (PMID 37634008, 2023). "The researchers found that in ovarian cancer cells with ARID1A mutation, PIK3IP1, a direct target gene of ARID1A and EZH2, was up-regulated after EZH2 was inhibited, leading to cell death by inhibiting the PI3K-AKT signaling pathway." (PMID 38008753, 2023). "EZH2 phosphorylation at T372 reduces ovarian cancer cell proliferation, migration and tumor formation." (PMID 37803297, 2023). "Other reports have described a high level of H3K27me3 as an indicator of good prognosis; however, H3K27me3 is usually lost in ovarian cancer, contradictory to the oncogenic role of EZH2 as the H3K27me3 methyltransferase." (PMID 37210576, 2023). "According to RNA-seq analyses, CHD4 was positively correlated with EZH2 in ovarian cancer patients (p = 0.004)." (PMID 36681835, 2023). "We next analysed the relationship between CHD4 and methylation enzymes (DNMT1, DNMT3B, EZH2, and G9a) in ovarian cancer." (PMID 36681835, 2023). "Overall, we observed that EZH2 is essential for CHD4-mediated repression of ovarian cancer tumorigenesis." (PMID 36681835, 2023). "EZH2 has been also studied in most common gynecologic malignancies such as cervical, endometrial and ovarian cancer." (PMID 38146588, 2023). "Among the different classes of ovarian tumors, EZH2 overexpression is most common in epithelial ovarian cancer, where it is observed in ~66% of primary tumors." (PMID 36359771, 2022). "One of the epigenetic modifiers, EZH2 has been studied to promote ovarian cancer chemoresistance and recurrence." (PMID 35310909, 2022). "Then, LINC00702 was reported to accelerate the progression of ovarian cancer by acting with EZH2 to repress KLF2 transcription." (PMID 36566321, 2022). "This putative proangiogenic role for EZH2 in ovarian cancer is supported by in vitro studies where EZH2 knockdown reduced human umbilical vein endothelial cell (HUVEC) migration and endothelial tube formation in Matrigel." (PMID 36359771, 2022). "For instance, silencing hsa-circ-0026123 is a promising strategy that enhances the expression level of miRNA-124-3p, leading to EZH2 down-regulation in ovarian cancer cells to inhibit their migration and growth." (PMID 35236381, 2022). "The oncogenic contribution of EZH2 has shown in multiple kinds of the human cancers such as the breast and ovarian cancers so that it induces the expression of the tumor inhibitor genes." (PMID 34923811, 2022). "For instance, lncRNA SNHG7 can be activated by SP1 and interact with EZH2 and confer oncogenic functions in ovarian cancer." (PMID 36105363, 2022). "Further studies focused in more detail on the potential mechanism and targets of EZH2 in cisplatin-resistant ovarian cancer cells." (PMID 36230683, 2022). "EZH2 levels in ovarian cancer correlate strongly with advanced cancer stage, metastasis, and tumor vascularization." (PMID 36359771, 2022). "It has been reported that EZH2 increases ovarian cancer growth and promotes cell cycle progression through transcriptional activation of CDKN1C." (PMID 35236381, 2022). "More recently, histone methylation mediated by both G9A and EZH2 has been identified as an important pathway that influences the immune system in ovarian cancer and multiple other malignancies, including multiple myeloma and hepatocellular carcinoma." (PMID 35131874, 2022). "Lastly, EZH2 overexpression promotes stemness in a sub-population of epithelial ovarian cancer cells." (PMID 36359771, 2022).
ovarian carcinoma (continued). "Ovarian cancer maintains high expression of miR-101 and miR-26a, which constrained expression of EZH2 in T cells, to dampen the function of CD8+ T cells." (PMID 35982471, 2022). "In epithelial ovarian cancer cell lines, EZH2 levels correlate inversely with TIMP2 levels via the EZH2 methylation of H3K27 on the TIMP2 promoter." (PMID 36359771, 2022). "In ovarian cancer, these changes are most often the result of the overexpression of EZH2, leading to H3K27 hypermethylation." (PMID 36359771, 2022). "This suggests that EZH2 is necessary for epithelial ovarian cancer tumor survival to hold tumor suppressors in check." (PMID 36359771, 2022). "EZH2 knockdown reduced spheroid formation by 50% by an epithelial ovarian cancer cell line, suggesting that EZH2 functions in proliferation and stemness." (PMID 36359771, 2022). "The link to metastasis is also supported by cell biology as EZH2 siRNA knockdown in SKOV3 cells (an epithelial ovarian cancer patient line) significantly reduced cell migration and invasion in cell culture assays." (PMID 36359771, 2022). "Epithelial ovarian cancer cell viability has been shown to be dependent on EZH2 expression, and therefore, EZH2 inhibition, is a promising targeted therapeutic strategy, highlighting the potential of miR-101 in the treatment of epithelial ovarian cancer." (PMID 36360295, 2022). "PVT1 inhibits the expression of miR-214 in ovarian cancer cells by regulating the epithelial-mesenchymal transition process and its interaction with EZH2, which promotes the progression of ovarian cancer." (PMID 39280958, 2022). "They documented that EZH2 was overexpressed in cisplatin-resistant ovarian cancer cells (A2780/DDP) compared with cisplatin-sensitive cells (A2780)." (PMID 36230683, 2022). "One study found that overexpression of EZH2 across all grades of epithelial ovarian cancer was strongly correlated (p < 0.001) with decreased overall survival (median survival of 2.5 years for EZH2 overexpression vs. 7.33 for EZH2 normal)." (PMID 36359771, 2022). "A few studies have examined the role of miRNA/EZH2 interaction in ovarian cancer and more experiments are needed to delineate the mechanisms of action." (PMID 35236381, 2022). "Nevertheless, EZH2 expression supports the activity of tumor-specific effector T cells in ovarian cancer and restrains the expansion of MDSCs in murine models of lung and colon cancer, indicating that EZH2 inhibitors can also impair antitumor immunity." (PMID 33922336, 2021). "Metformin has been reported to decrease the level of H3K27me3 accompanied by EZH2 repression in ovarian cancer cells through activation of AMPK28,35." (PMID 34815475, 2021). "The CRISPR and Cas9 endonuclease system was used to establish an EZH2-knockout SK-3rd ovarian cancer cell line." (PMID 33408782, 2021). "Here, we aimed to investigate the specific mechanism by which EZH2 regulates CSCs to result in chemoresistance and poor prognosis of ovarian cancer." (PMID 33408782, 2021). "It has also been shown that pT311-EZH2 inhibits ovarian cancer cell proliferation by suppressing EZH2-mediated H3K27me3 on PRC2 target genes." (PMID 34775498, 2021). "To examine the effect of EZH2 on CSC populations in ovarian cancer, we first compared the protein level of EZH2 in SKOV3, SK-1st, SK-2nd and SK-3rd cells by Western blot and found a gradual increase in the EZH2 level." (PMID 33408782, 2021). "EZH2 is aberrantly overexpressed in various malignant tumors, such as prostate, breast, and ovarian cancers." (PMID 33778063, 2021). "The elevation of H3K27me3 via enhancer of zeste 2 polycomb repressive complex 2 subunit (EZH2) overexpression abrogated the effect that metformin had on cell proliferation and apoptosis in an ovarian cancer cell line, SKOV3 and ES2 cells." (PMID 33578894, 2021). "More importantly, the expression of EZH2 and pCHK1 is critical for predicting the prognosis of ovarian cancer." (PMID 33408782, 2021).
ovarian carcinoma (continued). "Ectopic EZH2 expression increased the sphere formation ability of ovarian cancer cells, whereas EZH2 downregulation in CSCs reduced self-renewal, chemotherapy resistance and tumor-initiating capacity." (PMID 33408782, 2021). "For example, inhibition of EZH2 promotes epithelial-to-mesenchymal transition in ovarian cancer cells." (PMID 33669182, 2021). "Overexpression of EZH2 has been observed in a wide variety of cancers including ovarian cancer where its upregulation has been shown to occur with acquired cisplatin resistance in ovarian cancer cell lines and xenografts." (PMID 34140011, 2021). "Other SWI/SNF altered cancers that are dependent on EZH2 include SS18-SSX translocated synovial sarcoma, ARID1A-mutated ovarian cancer, SMARCA4-mutated lung and ovarian cancers, and PBRM1-mutated renal cancers." (PMID 34617019, 2021). "Consistent with the defect in HR, EZH2 inhibition selectively sensitized ovarian cancer cell lines with sufficiently high MAD2L2 levels to PARP inhibitors in both orthotopic and patient-derived xenografts." (PMID 34745220, 2021). "EZH2 + CD8 + T cell numbers and the percentage of EZH2 + CD8 + T cells in tissue samples of ovarian cancer patients were significantly associated with improved overall survival." (PMID 34001289, 2021). "We have previously demonstrated that E2F6-mediated EZH2 repression is responsible for the epigenetic silencing of miR-193a in ovarian cancer." (PMID 33718136, 2021). "The expression of EZH2 or pCHK1 in platinum-resistant ovarian cancer tissues was significantly increased compared with that in platinum-sensitive tissues." (PMID 33408782, 2021). "To understand the action and potential of EZH2 inhibition in ovarian cancer, we must first discuss the mechanism of action of these PRC2 antagonists whose loss results in EZH2 dependency in cancer." (PMID 34213777, 2021). "Our data strengthen those from an earlier study showing that EZH2 acts a critical factor in promoting ovarian cancer chemoresistance and proliferation." (PMID 33408782, 2021). "In this context, there is a pressing need to identify more specific mechanisms by which EZH2 leads to the development and progression of ovarian cancer." (PMID 33408782, 2021). "In ovarian cancer cells, the anti-tumor effect of metformin has been reported to be mediated through reduced expression of EZH2 and suppressed level of H3K27me328." (PMID 34815475, 2021). "In recent years, it has become clear that, like the majority of other cancers, many epigenetic regulators are altered in ovarian cancer, including EZH2, SMARCA2/4 and ARID1A." (PMID 34213777, 2021). "Our data uncover a previously undescribed role of EZH2 in regulating CHK1-dependent ovarian CSC expansion and show that EZH2 has a critical role in ovarian cancer chemoresistance and progression." (PMID 33408782, 2021). "The metabolic enzyme EZH2 was connected to deregulated metabolites L-lysine in cervical, breast, and ovarian cancer." (PMID 34790674, 2021). "LINC00511 plays an oncogenic function by interacting with EZH2 and repressing P21 expression in ovarian cancer cells." (PMID 34461858, 2021). "We evaluated associations between EZH2/CHK1 expression and the chemoresistance and prognosis of ovarian cancer patients." (PMID 33408782, 2021). "EZH2 plays an important role in promoting cell proliferation, migration, and invasion in ovarian cancer by regulating the core steroid biosynthesis gene via H3K27me3 methylation." (PMID 33163485, 2020). "The results suggested that EZH2/H3K27Me3 and pEZH2 predicted chemotherapy response and progression-free survival in ovarian cancer." (PMID 32435534, 2020). "We first assessed the association of independent EZH2, H3K27me3, pAkt1, pS21EZH2 and EZH2/H3K27me3, pAkt1/pS21EZH2 combination with clinical characteristics of ovarian cancer patients such as age, histology, FIGO stage, tumor type and chemotherapy response." (PMID 32435534, 2020).
ovarian carcinoma (continued). "Wei and his colleagues found that the AMPK-mediated phosphorylation of EZH2 at T311 decreases its methyltransferase activity to relieve the EZH2-dependent epigenetic silencing of its target genes and subsequently suppresses ovarian cancer tumorigenesis." (PMID 33308321, 2020). "Another study found that culturing T lymphocytes in conditioned media from ovarian cancer cells decreased expression of the methyltransferase EZH2 in T cells and their polyfunctionality, and these effects were abrogated upon glucose supplementation." (PMID 32367803, 2020). "The positive feedback loop between EZH2 and miRNAs maintains the high expression of EZH2, thus promoting the malignant proliferation of ovarian cancer by regulating proliferation-related proteins." (PMID 33718109, 2020). "EZH2 overexpression has been reported in ovarian cancer, predominantly in the context of epithelial ovarian neoplasms." (PMID 33050946, 2020). "Recent study revealed that EZH2 regulated cisplatin resistance in ovarian cancer through c-Myc-miR-137-EZH2 axis." (PMID 32723346, 2020). "Our RNA immunoprecipitation experiment indicated that PVT1 bound histone methyltransferase enhancer of zeste homolog 2 (EZH2), and regulated the expression of target gene, including p57, and consequently altered ovarian cancer cell biology." (PMID 33763107, 2020). "In conclusion, this study suggested that EZH2/H3K27Me3 and pEZH2 predicted chemotherapy response and progression-free survival in ovarian cancer." (PMID 32435534, 2020). "We confirmed that a feedback loop exists between EZH2 and miRNA that maintained EZH2 overexpression, thus promoting ovarian cancer proliferation in vivo and in vitro." (PMID 33718109, 2020). "In summary, EZH2 plays an important role in promoting cell proliferation, migration, and invasion in ovarian cancer by regulating the core gene of steroid biosynthesis via H3K27me3." (PMID 33163485, 2020). "It is known that the expression of EZH2 in drug-resistant cells is significantly higher than sensitive cells of ovarian cancer, multiple myeloma and other cancers." (PMID 32859239, 2020). "In the present study, we proposed and verified a positive feedback loop between EZH2 and miRNAs that maintained a high EZH2 expression in ovarian cancer." (PMID 33718109, 2020). "Our previous study found that EZH2 is highly expressed in ovarian cancer compared with that in benign and borderline ovarian tumors." (PMID 33718109, 2020). "The effect of EZH2 on ovarian cancer was evaluated in vitro with MTT, wound healing, Transwell, and apoptosis assays and in vivo with a xenograft model." (PMID 33163485, 2020). "In conclusion, our data suggest a positive feedback loop exists between EZH2 and miRNAs in epithelial ovarian cancer that maintains high EZH2 expression and promotes tumor cell proliferation by regulating cell proliferation-related proteins." (PMID 33718109, 2020). "The results showed that steroid biosynthesis was activated after EZH2 knockout in ovarian cancer cells and that the hub gene of steroid biosynthesis, CYP27B1, was upregulated." (PMID 33163485, 2020). "Recently, studies have demonstrated that the overexpression of EZH2 correlates with a high proliferative index and tumor grade in ovarian cancer." (PMID 33163485, 2020). "SMARCA4 and EZH2 expression was assessed by RT-PCR in 238 epithelial ovarian cancers (OCs) and put in relation to clinico-pathological parameters and patients’ outcome." (PMID 33230143, 2020). "EZH2 acts as an oncogene through canonical pathway EZH2/H3K27Me3 and uncanonical pathway pAkt1/pS21EZH2 in many solid tumors including ovarian cancer." (PMID 32435534, 2020).
ovarian carcinoma (continued). "In the present study, we knocked out EZH2 in ovarian cancer cells via the clustered regularly interspaced short palindromic repeats (CRISPR)/Cas9 system to explore its biological effects in vitro and in vivo." (PMID 33163485, 2020). "A recent study reported that EZH2 phosphorylation at T372 reduced ovarian cancer cell proliferation, migration and tumor formation." (PMID 32435534, 2020). "In a previous study, the role of EZH2 promoting cancerous cell proliferation and invasion in ovarian cancer was also been reported." (PMID 33292225, 2020). "In the present study, we found that Et-miRNA can inhibit the expression of EZH2 and impair the proliferation of ovarian cancer in vivo and in vitro." (PMID 33718109, 2020). "After silencing CYP27B1 with siRNA, the proliferation, migration, and invasion of ovarian cancer cells were significantly suppressed, indicating that the function of EZH2 in promoting ovarian cancer progression was achieved by the inhibition of CYP27B1." (PMID 33163485, 2020). "Our findings provide new insights into the regulatory mechanism between EZH2 and miRNAs in ovarian cancer and some evidence for the application of miRNA related agents and EZH2 inhibitors in ovarian cancer treatment." (PMID 33718109, 2020). "In this study, we demonstrated a positive feedback between EZH2 and miRNAs in epithelial ovarian cancer that promoted malignant proliferation by maintaining the high expression of EZH2." (PMID 33718109, 2020). "EZH2, H3K27Me3, pAkt1 and pS21EZH2 were universally expressed in ovarian cancer specimens with a positive expression rate of 81.54% (53/65), 88.89% (48/54), 63.07% (41/65) and 75.38% (49/65)." (PMID 32435534, 2020). "According to a previous study, the overexpression of EZH2 promotes the survival of ovarian cancer cells via trimethylation of ARHI, a negative regulator of cancer cell growth and progression." (PMID 33163485, 2020). "EZH2, H3K27Me3, pAkt1 and pS21EZH2 expression were evaluated by tissue micro-array and immunohistochemistry in a cohort of ovarian cancer patients." (PMID 32435534, 2020). "On the other hand, our results revealed that EZH2 phosphorylation at S21 associated with chemotherapy resistance and predicted poor PFS in ovarian cancer patients suggesting an oncogenic role of EZH2-pS21." (PMID 32435534, 2020). "In the present study, the IHC results for the 160 ovarian cancer samples revealed an inverse correlation between the expression levels of EZH2 and CYP27B1, which was significantly associated with the prognosis of ovarian cancer." (PMID 33163485, 2020). "Further experimental validation and mechanistic investigation indicate that LINC00511 exerts oncogenic function in ovarian cancer cells through interacting with EZH2 and repressing P21 expression." (PMID 31016892, 2019). "Among methyltransferases in ovarian cancer, the Enhancer of Zeste 2 (EZH2)—also known as Polycomb Repressive Complex 2 (PRC2)—has emerged as an important epigenetic regulator of ovarian cancer biology." (PMID 31426393, 2019). "In similar context, another study highlighted silencing of ARHI in ovarian cancer which was synergistically mediated by Enhancer of zeste homolog 2 (EZH2) induced H3K27me3 and DNA methylation." (PMID 31608277, 2019). "The levels of EZH2 are significantly upregulated in ovarian cancer and correlate with a poor prognosis of ovarian cancer patients." (PMID 31426393, 2019). "For example, EZH2 inhibitor inhibits the growth of ovarian cancer cells which are positive for arginine methyltransferase PRMT4/CARM1, which itself is upregulated in ovarian cancer." (PMID 31426393, 2019). "MiR-138-5p has been reported as a tumor suppressor in several types of cancer such as multiple myeloma and ovarian cancer by targeting EZH2 and survivin." (PMID 31783879, 2019). "Simultaneously, knockdown of EZH2 expression also up‐regulated P21 expression in ovarian cancer cells." (PMID 31016892, 2019).